IQCK (IQ motif containing K)
Synonyms: MGC35048; FLJ36575
Tractability: PROTAC: ubiquitination databases record sites on it.
Gene: Protein-coding gene on chromosome 16 (19,716,456 to 19,858,467, forward strand). Ensembl gene ENSG00000174628.
Subcellular location (Human Protein Atlas): Nuclear speckles; Cytosol
Genetic constraint (gnomAD): Loss-of-function variants: 15 observed, 14.51 expected, observed/expected ratio (o/e) 1.03, 90% interval 0.69 to 1.58. The upper end of that interval is the gene's LOEUF score, 1.58, which puts it in group 6 of 6, group 1 being the genes least tolerant of losing a copy. Missense variants: 288 observed, 250.04 expected, observed/expected ratio (o/e) 1.15, 90% interval 1.04 to 1.27. Synonymous variants: 91 observed, 91.73 expected, observed/expected ratio (o/e) 0.99, 90% interval 0.84 to 1.18.
Homologues: Orthologues: chimpanzee IQCK (98% identical), macaque IQCK (94% identical), dog IQCK (74% identical), mouse Iqck (72% identical), rabbit IQCK (71% identical), pig IQCK (71% identical), rat Iqck (71% identical), guinea pig IQCK (68% identical), tropical clawed frog IQCK (43% identical).
Diseases named in the same sentence as IQCK in open-access papers:
IQCK is named in the same sentence as 12 diseases in open-access papers, as found by Europe PMC text mining. Sharing a sentence is not in itself a finding about the gene and the disease. The quoted sentences say what the papers report.
Alzheimer disease (4 papers, 2021 to 2025). A progressive, neurodegenerative disease characterized by loss of function and death of nerve cells in several areas of the brain leading to loss of cognitive function such as memory and language. "Emerging studies indicate that the IQ‐motif‐containing protein K (IQCK) is a novel risk factor for Alzheimer's disease (AD), an age‐associated disease." (PMID 40604342, 2025). "An IQ motif containing protein K (IQCK) was recently identified by several investigators as an Alzheimer’s disease risk gene." (PMID 35928571, 2022). "Importantly, a genetic meta-analysis of patients diagnosed with Alzheimer’s disease confirmed IQCK as a risk gene and ranked it at the top among other analyzed risk factors for AD." (PMID 35928571, 2022). "Variants in other interaction partners of NCOA3 including insulin growth factor 1 (IGF1 rs5742643), HNF1 homeobox A (HNF1A rs1800574 and rs56348580), and IQ motif containing K (IQCK rs7185636) were associated with systolic blood pressure, type 2 diabetes, or Alzheimer’s disease, respectively." (PMID 34864818, 2021). "In an exploratory cross-disorder meta-analysis of the Genetic and Environmental Risk in Alzheimer’s Disease (GERAD) study for both obesity and AD, an IQ motif containing K gene (IQCK) was identified that showed the same direction of a risk allele for both AD and obesity." (PMID 35928571, 2022). "Moreover, C20orf85 has been linked to lung cancer and DYDC1 seems to be involved in acrosome biogenesis, although IQCK has recently been highlighted in several studies regarding Alzheimer’s disease." (PMID 34573434, 2021).
amyloid (3 papers, 2022 to 2025). "IQCK were increased expression in AD brains and amyloid plaques, and it may play a pathogenic role in either Aβ generation or amyloid plaque deposition in AD." (PMID 37416324, 2023). "It is also important to note that the IQCK protein is present in amyloid plaques, suggesting that it may play a pathogenic role in amyloid plaque development or Aβ generation." (PMID 35928571, 2022). "Importantly, increased IQCK immunoreactivity was found within the amyloid plaques, implying that IQCK may have an important causative role in AD." (PMID 40604342, 2025). "Furthermore, the IQCK protein was found in amyloid plaques, suggesting that IQCK may play a pathogenic role in either Aβ generation or amyloid plaque deposition in AD." (PMID 35928571, 2022).
multiple system atrophy (3 papers, 2020 to 2025). Multiple system atrophy (MSA) is a neurodegenerative disorder characterized by autonomic failure (cardiovascular and/or urinary), parkinsonism, cerebellar impairment and corticospinal signs with a median survival of 6-9 years. "While the function of IQCK is unclear, the circular form of IQCK transcripts (circRNA) is overexpressed in multiple system atrophy, a neurodegenerative disease." (PMID 37808784, 2023). "Another research group performed circRNA sequencing of the brain samples from multiple system atrophy (MSA) patients and identified five circRNAs, namely IQCK, MAP4K3, EFCAB11, DTNA, and MCTP1, that were overexpressed in the white matter of the cortical tissue." (PMID 33269108, 2020). "Parallel studies also confirmed IQCK mutation in congenital anomaly limb body wall complex (LBWC) and a robustly increased circular IQCK RNA but not linear RNA in the multiple system atrophy (MSA) brains, especially in the white matter of the frontal cortex." (PMID 40604342, 2025).
Obesity (2 papers, 2022 to 2023). Accumulation of substantial excess body fat. "IQCK as a risk locus in obesity was also confirmed by another independent study." (PMID 35928571, 2022). "Thus, after the application of stringent quality control protocols, these multiple studies have confirmed the importance of the IQCK gene in increasing the risk of not only AD but also OCD and obesity." (PMID 35928571, 2022).
neuroblastoma (1 paper, 2022). Neuroblastoma (NB) is the most common solid, extracranial childhood tumor. "Similar to SH-SY5Y neuroblastoma cells, an intense IQCK immunoreactivity was detected in the cytoplasm as well as the nucleus in both mouse and human brain cells." (PMID 35928571, 2022). "Since SH-SY5Y is a neuroblastoma cell line that can be differentiated into various functional neurons, IQCK immunoreactivity in these cells suggests that IQCK might be expressed in neurons." (PMID 35928571, 2022). "Our data on subcellular localization provide the first direct evidence of IQCK expression in both the nucleus and the cytoplasm in multiple cell types including neuroblastoma cells but not microglial cells." (PMID 35928571, 2022). "Therefore, in this study, we show by immunocytochemical (ICC) staining that IQCK is expressed in both the nucleus and the cytoplasm of SH-SY5Y neuroblastoma cells as well as HeLa cells but not in either HMC3 microglial or CHO cells." (PMID 35928571, 2022).
IQCK also shares sentences with these, for which no sentence is quoted: bipolar disorder (1 paper); chronic obstructive pulmonary disease (1); lung carcinoma (1); neurodegenerative disease (1); oral cancer (1); tauopathy (1); type 2 diabetes (1).